CD44 (CD44 molecule (IN blood group))
Diseases named in the same sentence as CD44 in open-access papers (continued):
Sharing a sentence is not in itself a finding about the gene and the disease.
cancer (continued). "Targeting CD44 using peptides or antibodies has drawn great attention in cancer therapeutics but challenges remain because of abundant expression of CD44 in normal tissues including bone marrow, liver, spleen, and skin." (PMID 31416894, 2019). "The overexpression of CD44 on cancer cells redirects a number of oncogenic pathways including the central Pi3K/Akt/NF-kB pathway, leading to cancer progression and malignancy." (PMID 30943985, 2019). "Immunocytochemical double staining of the lung cancer stem cell markers CD133 and CD44 confirmed the isolation of cancer stem cells." (PMID 31804333, 2019). "The interaction between CD44 and osteopontin as a potential basis for cancer progression and metastasis formation is known for a long time." (PMID 31731625, 2019). "Cancer stemness marker CD44 level was also elevated through MCT-1 induction (1.98-fold) but decreased upon MCT-1 knockdown (0.28-fold) than the controls in mammospheroids as detected by qRT-PCR." (PMID 30885232, 2019). "For example, CD44 is a cell surface molecule that has been shown, through AS events, to play a role in cancer." (PMID 31443718, 2019). "Stimulation with SHH resulted in an up-regulation of cancer stemness in EC sphere cultures, as indicated by increased sphere formation after sorting for CD44+/CD24− EC cancer stem-like cell (CSC) population." (PMID 31200527, 2019). "Different morphological structures were shown to represent transcriptionally distinct tumor cell populations differing in the number of CD44+CD24− cancer stem cells, epithelial and mesenchymal features, and enrichment of cancer invasion signaling pathways." (PMID 31344926, 2019). "Cytometry analysis of the proportion of cancer stem cells (CD44+/CD24-) isolated with MACS was > 99%." (PMID 31612865, 2019). "The expression of the Wnt/β-catenin pathway target genes, particularly those related to cancer, such as CD44, S100A4, MMP7, and LBH, was significantly increased in GC tumors compared with that in normal tissue." (PMID 30965636, 2019). "miR-302a expression was decreased in most cancer tissues, which is consistent with the qPCR results, and NFIB and CD44 expression was increased in the corresponding cancer tissues compared with the matched adjacent normal tissues." (PMID 31754405, 2019). "Once the nanoparticles (TCiGNPs) accumulate in solid tumors through enhanced permeability and retention (EPR) effect, HA would intrinsically target cancer cells because of CD44 expression on the cancer cells 33-34." (PMID 31695790, 2019). "The appearance of double positive CD133/CD44 cancer cells has been characteristically found in several highly metastatic tumors of colon, liver, pancreas, and gallbladder." (PMID 31139149, 2019). "To evaluate the interaction between LETM1 expression and the stem cell like characteristics of LETM1 positive cells, we analyzed and compared its expression with that of other cancer stemness-related genes such as CD44, LSD1, Sox2 and Sox9." (PMID 31500591, 2019). "HA is a physiologic glycoprotein used as moiety to functionalize nanocarriers to target cancer cells overexpressing CD44, one of the principal HA receptors." (PMID 31509965, 2019). "The hydrophilic HA served as the targeting ligand for cancer cells overexpressing CD44, the HA receptor." (PMID 31060303, 2019). "Since some cancers originate from progenitor-like cancer-initiating cells, which commonly express CD44, small molecule inhibitors of CD44:HA binding are also being developed." (PMID 31134064, 2019). "Taken together, these data demonstrate that obASCs are promoting EMT, through downregulation of CD326 in tumors, increasing HLA+ CTCs enriched for the cancer stem cell maker CD44+CD24−, and have increased lung metastases." (PMID 31118047, 2019). "Immunohistochemical expression of HDAC6, hypoxia inducible factors-1α (HIF-1α), programmed death-1 ligand (PD-L1), CD44 (cancer stem cell marker), and ARID1A was analysed for 106 OCCC patients." (PMID 30787326, 2019).
cancer (continued). "In fact, as one of the cancer stem cell marker, more than 20 isoforms of CD44 exists due to RNA alternative splicing, leading to different proteins in different cancer tissue subtypes." (PMID 31462894, 2019). "EpCAM has been used in combination with CD44 as a marker to efficiently isolate cancer stem cells in different cancer entities such as colon, breast, pancreas and prostate carcinomas." (PMID 31225512, 2019). "YBX1 is also reported to bind to CD44 and CD49f promoter and enhance CD44 expression that promotes cancer cell growth and drug resistance in breast cancer." (PMID 31358880, 2019). "CD44+ population of PCa cells exhibit cancer stem cell (CSC) characteristics and correlate to poor survival of PCa patients." (PMID 30935014, 2019). "Owing to its specific binding affinity for CD44-overexpressing cancer cells, HA has been used extensively to prepare amphiphilic derivatives, capable of self-assembling into the nano-sized particles as a potential drug carrier for targeted cancer therapy." (PMID 31795253, 2019). "Subsequent ablation of CD44 led to the inhibition of glycolysis, an increase in ROS, and the enhancement of chemotherapeutic drug effect in these cancer cells." (PMID 31505803, 2019). "These nanoparticles (particle size was 73.2 ± 3.8 nm) selectively target cancer cells by CD44 endocytosis and have an anti-cancer effect after laser irradiation in in vitro and in vivo models." (PMID 31835293, 2019). "Studies in PDACs have shown that high expression of CD44 correlates with presence of cancer stem cells (CSC)." (PMID 31100813, 2019). "Small ubiquitin-like modifier (SUMO)-conjugated TFAP2A transcription factor induces the expression of CD44, which maintain the cancer stemness characteristics of breast and colorectal CSCs30." (PMID 30944375, 2019). "This evidence, combined with our findings that mTOR signaling, mEAK-7, and S6K2 are upregulated in CD44+/CD90+ cancer cell populations, suggests that mEAK-7 is involved in mTOR signaling in CSCs." (PMID 31288154, 2019). "The CD44+CD24low population is enriched for cancer stem cells (CSCs) although most cells in this population are not true CSCs." (PMID 31069797, 2019). "PDX tumors grown in the presence of obASCS in SCID/beige mice had increased circulating HLA1+ human cells as well as increased numbers of CD44+CD24− cancer stem cells in the peripheral blood." (PMID 31118047, 2019). "FAM83D promotes HCC recurrence by promoting CD44 expression and CD44+ cancer stem cells malignancy via activating the MAPK, TGF-β and Hippo signaling pathways." (PMID 30910840, 2019). "To determine the effects of IL-6 on cancer stem cells, we measured by flow cytometry the expression of two colorectal CSCs markers, namely, CD44 and CD133." (PMID 30804456, 2019). "It is well accepted that BMI-1 is necessary for self-renewal in both cancer and normal stem cells, and CD44 is also one of the most well-known CSC biomarkers." (PMID 30621095, 2019). "CD44 is a family of cell surface glycoproteins that are involved in cell–cell interactions, cell adhesion, and migration in many malignant tumors." (PMID 30943985, 2019). "DOX- and HA-decorated graphene oxide nanosheets (HSG–DOX) have been synthesized and successfully accumulated into CD44-over-expressing MDA–MB–231 cancer cells by the enhanced permeability and retention (EPR) effect and CD44 endocytosis." (PMID 31266194, 2019). "The adhesion receptor CD44 contributes to various diseases, the most widely studied being various cancers." (PMID 30909497, 2019). "Beyond increased drug resistance, cells also show enhanced cancer stem like cell populations expressing Oct-4, CD117 and CD44, which are tied to cancer dedifferentiation metastasis and self-renewal." (PMID 31323899, 2019). "Hyaluronic acid, which is a ligand of the cancer stem cells biomarker CD44, was used for the coating of solid lipid nanoparticles loaded with vorinostat in order to target CD44 expressing cancer cells." (PMID 30759891, 2019).
cancer (continued). "gPTX-IL should quickly recognize the CD44 positive cancer cells and retain on the cell surface due to the antibody, implying that the potential therapeutic effect should be high." (PMID 30818864, 2019). "Because of elevated expression of CD44 in cancer cells and high affinity between CD44 and HA, a variety of different HA-decorated nanocarriers are utilized for targeted cancer therapy." (PMID 30909497, 2019). "CD44+ has been reported to have the potential to be a marker of poor prognosis and to be involved in radio and chemotherapy resistance in several cancers." (PMID 31726667, 2019). "In turn, CD44 is a major HA‐binding cell surface receptor that is ubiquitously expressed on cells such as leukocytes, fibroblasts and cancer cells." (PMID 30637950, 2019). "In many cancers of epithelial origin, such as breast cancer, cluster of differentiation 44 (CD44) is a main up-regulated HA receptor on the cancer cell surface." (PMID 31057402, 2019). "These sphere-dispersed (sphere cells) cells had elevated mRNA levels of important cancer stem cell (CSC) makers including CD44, CD133, ALDH, ABCG2, OCT4, and Nanog compared with their parental cells in both OC-3-IV and C9-IV3 sublines." (PMID 30782177, 2019). "Recent studies have confirmed that PGCCs possess properties of cancer stem cells, with the expression of the cancer stem cell markers CD44 and CD133, and therefore, promote tumor maintenance and recurrence." (PMID 31025548, 2019). "Apart from direct and fatal stimuli on cancer cell membrane system with CSC marker CD44 and CD133 expression level reduced, our studies have defined that GrA down-regulated the expression level and altered the distribution pattern of CD47." (PMID 31139022, 2019). "This was demonstrated by knocking down CD44 expression in the MDA-MB-468 cancer cells, by knocking out CD44 in the 3T3HAS3 fibroblast cells, and by grafting these cells into the nude mice host system." (PMID 31762938, 2019). "Numerous researchers have revealed that a particular subdivision of CTCs can express stem cell markers (e.g., CD133 or CD44), can have cells with cancer stem cell characteristics, and can thus be considered circulating cancer stem-like cells (cCSCs)." (PMID 31791269, 2019). "Immunohistochemical analysis of vimentin and CD44 confirmed the evidence that in the presence of microcalcifications, both benign and malignant breast lesions are characterized by numerous breast cells with a mesenchymal phenotype." (PMID 31718020, 2019). "Another study indicated that HA binding to CD44 promotes recruitment of adaptor and/or linker molecules with CD44 in cancer cells." (PMID 31293964, 2019). "In 8 out of 10 cases examined, the vast majority of cancer cells (80–100%) were CD44+ indicating that these tumors were, indeed, highly enriched in bCSCs." (PMID 31627418, 2019). "As in other cancer types, CD44+ cells have been reported to possess the unique properties of CSCs in head and neck squamous carcinoma (HNSCC)." (PMID 31137841, 2019). "To further dissect the cellular and molecular mechanisms involved in HA-mediated oncogenesis, we decided to focus on the interaction between HA and its binding receptor, CD44, in a variety of cancer cells." (PMID 31293964, 2019). "FACS analysis revealed that docetaxel-resistant PCa cells contain higher CD44+ population, implying that these cells have higher cancer stem cell population." (PMID 30935014, 2019). "In a hypoxic environment, CD44 is highly expressed by CAFs that in turns helps mediate cancer cell migration and stemness sustainability." (PMID 31709180, 2019). "A previous study found that CD44 is frequently located in specialized microdomains in the plasma membrane, so-called lipid rafts of cancer cells." (PMID 31293964, 2019).
cancer (continued). "CD44 levels were significantly increased in cancer cells of LTB compared to those of STB, based on fluorescence-activated cell sorting (FACS) analysis." (PMID 31315262, 2019). "Surface marker CD44 plays important role in epithelial-mesenchymal transition and cancer stem cell phenotype." (PMID 31049070, 2019). "CD44 is a cancer stem cell marker, and its expression in RGK45 cells was higher than that in RGK36 cells." (PMID 30733583, 2019). "Unexpectedly, we observed that miR-34a is epigenetically controlled by a ceRNA mechanism through the 3′UTR of c-Myc, leading to upregulation of CD44 and cancer progression." (PMID 31569404, 2019). "In the present study, we propose that Etv1 is a nuclear transcriptional factor suppressed by the TGIF1 repressor, and Etv1 upregulation mediated by TGIF1 ablation confers to increase Has2 activity and activate the HA/CD44 cancer stemness pathway in PDAC." (PMID 31109321, 2019). "Due to selective targeting recognition of HA, these NPs were successfully accumulated to CD44-over-expressing MCF-7 cancer cells, compared to NHDF normal cells." (PMID 31266194, 2019). "Our results showed that FMR1-AS1 notably overexpressed in the CD44+ cancer stem-like cells within female ESCC patients." (PMID 30736860, 2019). "This revealed genes whose expression variation was governed by genomic state (clonality), such as CD44 antigen—a marker of tumorigenic cancer cells —of which around a quarter of expression variation is clone-specific." (PMID 30866997, 2019). "The results of the previous study revealed that BCc1 can reduce CD44 expression in cancer cell line; as a result, we can assume that BCc1 is able to affect CSCs." (PMID 30971278, 2019). "CD44 is a cell-surface glycoprotein involved in cell–cell and cell–matrix interactions and is known to be a cancer stem cell marker." (PMID 30650521, 2019). "CD44, a glycoprotein involved in cell–cell interactions, cell adhesion and migration, is a marker of stemness of CSCs for several cancer types, including prostate." (PMID 31878027, 2019). "Targeting TISCs by inhibiting CD44 signaling with blocking monoclonal antibodies (mAb) has emerged as a promising anti-cancer therapy." (PMID 31106150, 2019). "Collectively, CD44 is a critical regulator of cytoskeletal dynamics, cell motility, migration, and invasion in normal development and cancer progression." (PMID 31416894, 2019). "Detection of CD44-positive EVs would be a promising tool for diagnostics of cancers with changed CD44 expression." (PMID 30909497, 2019). "The cell surface adhesion receptor CD44 reportedly affects the development and progression of cancers." (PMID 31682231, 2019). "By combining HA with SA, a self-assembling biodegradable block-copolymer, made of natural body components was created, in which HA also acts as the homing ligand for cancer cells exhibiting CD44 overexpression." (PMID 31060303, 2019). "YAP/CD44 axis confers cancer stemness in MM cells and therefore enhance resistance against chemotherapy." (PMID 30935014, 2019). "Hyaluronic acid was used for its ability to target CD44, which is overexpressed in many types of cancer cells, while epigallocatechin gallate, the main component of green tea catechins, was chosen for its ability to bind to proteins." (PMID 30943985, 2019). "Collectively, our findings underscore a novel role of CD44 signaling in the maintenance of stemness and progression of cancer through SOX2 in AR‐independent PC3 cells." (PMID 30206982, 2019). "Although the function of diverse CD44 isoforms has been characterized in multiple cancers recently, the mechanisms that responsible for the splicing of different CD44 isoforms is relatively less known." (PMID 31857793, 2019). "HA has been extensively used for selective cancer targeting due to the overexpression of HA receptors (CD44) in cancer cells." (PMID 31861339, 2019).
cancer (continued). "CD44 is involved in several types of cancers, including pancreatic, colorectal, breast, and prostate cancer, as well as head and neck squamous cell carcinoma, and gastrointestinal cancer." (PMID 31608236, 2019). "CD44 is a transmembrane glycoprotein involved in cancer proliferation, metastasis, and drug resistance." (PMID 31754405, 2019). "Specifically, levels of the pVHL and RhoA were decreased, and the expression of HDAC1, CD44 (a cancer stem cell [CSC] marker), Snail, and vimentin (EMT markers) in normal hRECs and various renal tumor cell types (Caki-2, ACHN, and 798-o) was upregulated." (PMID 30872677, 2019). "In this regard, the analyses of treated rat carcinoma cells showed a CD44 and ALDH1A1 expression decrease and Bax expression increase." (PMID 30970626, 2019). "The expression of CD44 has been studied in various carcinomas and was correlated with metastatic potential." (PMID 34322276, 2019). "CD44+/CD117+ cancer stem cells isolated from the peritoneal fluid of HGSOC patients that had the ability to form tumors in mice, showed decreased levels of pyruvate dehydrogenase kinase (PDHK1) and increased expression of isocitrate dehydrogenase (IDH2)." (PMID 30231564, 2018). "On a cellular level, CD44-positive cells have been reported to contribute less than 10% to the total population of cancer cells while other sources place the share of CD44-positive cells in HNSCC tumors in the range of 60–95%." (PMID 29693014, 2018). "Of note, circulating miR-199a-3p level or its target CD44 have shown promising diagnosis or prognosis values in cancer." (PMID 30352835, 2018). "Hyaluronidases favor cancer progression via production of hyaluronan fragments which enhance cleavage of CD44 and thus induce cell motility." (PMID 29914429, 2018). "We also found that CD10 expression by the stromal cells, but not by the neoplastic cells, correlates significantly with the expression of cancer stem cell markers (CD44+/ALDH1+) (p = 0.002)." (PMID 29306324, 2018). "GS in T increased with development of cancer metastases, and was suppressed by knockdown of CD44 expressed in cancer cells, a molecule stabilizing cystine transporter (xCT) as part of cancer survival." (PMID 29674746, 2018). "Some of the KI67+ cells revealed undetectable CD44 staining (white asterisk), suggesting variable expression of CD44 marker at various stages of proliferation and differentiation of cancer cells as well as CSCs." (PMID 30121075, 2018). "CD44 is a transmembrane glycoprotein that acts as a HA receptor and is one a well-accepted cancer stem cell (CSC) surface markers." (PMID 30135409, 2018). "The CD44+/CD117+ cancer stem cells produced higher levels of oxygen radicals and had enhanced OXPHOS than the non-stem cell (CD44+/CD117−) population." (PMID 30231564, 2018). "In these cancer resistant rodents, the fibroblasts secrete high molecular weight hyaluronan which protects the animal from developing cancer by early contact inhibition and tissue homeostasis dependent on the CD44-Neurofibromin 2 pathway." (PMID 29883428, 2018). "The most important receptor of HA is ‘Cluster of Differentiation 44’ (CD44), a cell surface glycoprotein over-expressed by a number of cancers and heavily involved in HA endocytosis." (PMID 29670009, 2018). "In patients with metastatic gastric cancer, vismodegib did not lead to any clinical benefit except in a subgroup of patients with high levels of CD44 expressing cancer stem cells within the primary tumors." (PMID 30551640, 2018). "Among the cells, certain cancers, such as breast cancer, over-express CD44 and, for this reason, HA-based nano-carriers have been especially studied for cancer therapy and theranostics purposes." (PMID 29670009, 2018). "Cancer cells showed a higher expression of CD44 level when compared with normal cells and was recognized as a potential therapeutic target in cancer therapy." (PMID 29534519, 2018).